IL1B (interleukin 1 beta)
Diseases named in the same sentence as IL1B in open-access papers (continued):
Sharing a sentence is not in itself a finding about the gene and the disease.
Sepsis (continued). "Both IL-1β and IL-18 are involved in sepsis, sepsis-induced muscle failure and sepsis-induced cardiomyopathy." (PMID 35615361, 2022). "Analysis of plasmatic cytokines showed that, in all mouse strains, sepsis was accompanied by increase of IL-1β, IL-6, IL-10, TNF-α and IFN-γ." (PMID 36119089, 2022). "Compared to sepsis and vehicle groups, Montelukast pre-treatment groups had significantly reduced lung tissue levels of pro-inflammatory cytokines (IL-1B, IL-6, and IL-17)." (PMID 35928365, 2022). "In sepsis models, there is substantial evidence that neutrophils undergo pyroptosis and that interleukin 18 (IL-18) and interleukin 1 β (IL-1β) levels are elevated." (PMID 36713461, 2022). "Treatment of sepsis-exos significantly increased the serum levels of IL-1β and IL-18 72 h after surgery." (PMID 35345489, 2022). "Activation of this axis promotes increased expression/secretion of pro-inflammatory cytokines such as TNF-α, IL-6, IL-1β and IL-17, which in turn contribute to the cytokine storm and multiple organ failure (MOF) associated with sepsis." (PMID 36119089, 2022). "XBJI treatment reduces mortality, anal temperature, and the expression of inflammatory factors such as TNF-α, IL-1β, and IL-6 when administered to mouse sepsis models." (PMID 36361915, 2022). "Early in sepsis, Kupffer cells play an essential role in the removal of bacteria and endotoxins through the release of proinflammatory cytokines such as interleukin (IL)-1β, IL-6, IL-18, and tumor necrosis factor-alpha (TNF-α)." (PMID 36120368, 2022). "Sepsis related to IE is accompanied by local and strong systemic inflammatory response with elevated circulating IL-6, IL-2R and IL-1β concentrations." (PMID 36233404, 2022). "Rg4 also reduced the levels of TNF-α and IL-1β in the liver, which supported the anti-inflammatory activities of Rg4 on sepsis." (PMID 36142743, 2022). "On the other hand, elevations of IL-1β serum concentrations in human sepsis can be mild or irregular, are dependent on the phase of septic state, and, in addition, the kidney has a role in IL-1β removal in sepsis as long as diuresis is preserved." (PMID 35204131, 2022). "Increased IL-1β signaling is involved in many medical and psychiatric conditions such as tissue damage, sepsis, rheumatoid arthritis, as well as schizophrenia, and mood disorders." (PMID 35641947, 2022). "Compared with the respective levels in the control group, the mRNA and protein expression levels of KLF14 and the inflammatory factor IL-1β were increased in the PBMCs collected from sepsis patients." (PMID 34983946, 2022). "The levels of IL-6, TNF-α, and IL-1β in the miR-221 inhibitor group were significantly lower than those in the sepsis group (P < 0.05)." (PMID 35186224, 2022). "Specifically, evoked supernatant concentrations of TNF, IL-6, IL-1α, IL-1β, and IL-8 were all substantially less in assays of sepsis patients’ samples, despite greater baseline concentrations and ongoing inflammatory activity when compared to controls." (PMID 35981050, 2022). "Studies have shown that during the development of sepsis, inflammatory cytokines IL-1β and IL-6 work in concert to initiate the inflammatory response and have a negative inotropic effect on the myocardium." (PMID 35223094, 2022). "The NF-κB signaling pathway is one of the key regulatory pathways of inflammatory response, and the changes in the expression of pathway-related genes such as CD14, MyD88, TNF-α, IL-1β, and IL-1R play an important role in the development of sepsis." (PMID 35186224, 2022). "Based on the RFWK inhibitory motif, we designed an RFWK peptide inhibitor to target caspase-1/11 activity and found the inhibitor substantially suppresses GSDMD cleavage and IL-1β release, as well as LPS-induced sepsis in mice." (PMID 36322773, 2022).
Sepsis (continued). "Accumulating evidence indicates that NLRP3-mediated pyroptosis results in plasma membrane rupture and subsequently in a drastic release of powerful proinflammatory factors such as IL-1β, thereby resulting in a hyperinflammatory response to sepsis." (PMID 35136484, 2022). "By contrast, plasma levels of IL-1β showed a significant increase during CLP sepsis in both WT and CTTN KO mice." (PMID 35625756, 2022). "The results in this also showed that EA at ST36 inhibited the production of TNF-α, IL-1β, and IL-6 and increased IL-10 production in septic mice, suggesting its therapeutic effect on sepsis." (PMID 35722155, 2022). "Another top gene identified in this study was ELAVL1, which encodes HuR protein, playing a critical role in post-transcriptional regulation, splicing and suppression of thrombomodulin synthesis in interleukin-1β (IL-1β) treatment and sepsis." (PMID 35938548, 2022). "The plasma levels of TNF-α, IL-6, and IL-1β in the T2DM combined with the sepsis group were significantly higher than those in the control group (P < .001)." (PMID 35960063, 2022). "Recent studies have shown that IL-3 plays an essential role during early sepsis: IL-3 operates upstream of key CKs [e.g., IL-6, IL-1β, and tumor necrosis factor–α (TNF-α)], and high IL-3 levels increase the risk of CK storms." (PMID 36129990, 2022). "We observed that MIP-3α and IL-1β were decreased in sepsis, MIP-3α was negatively correlated with MDSCs/G-MDSCs, and IL-1β and IP-10 were positively correlated with M-MDSCs in sepsis patients." (PMID 35720398, 2022). "DHA27 plus tobramycin reduced the bacterial load in the spleen and lungs of sepsis model mice and levels of proinflammatory cytokines interleukin-1β (IL-1β) and interferon-γ (IFN-γ)." (PMID 36353502, 2022). "IL-1β levels were analyzed in the hippocampus after the environmental enrichment protocol in animals submitted to sepsis." (PMID 35798809, 2022). "The levels of IL-6, TNF-α, and IL-1β in the HECTD2siRNA group were significantly lower than those in the sepsis group (P < 0.05)." (PMID 35186224, 2022). "IL-1Ra, the antagonist to IL-1β, has been considered a novel treatment against sepsis since it inhibits excessive inflammation." (PMID 35811678, 2022). "Promote the release of pro-inflammatory factors TNF-α, IL-6, IL-1β, the occurrence of inflammatory response mediates organ damage, increase the mortality of sepsis." (PMID 35463634, 2022). "Proinflammatory cytokines, such as TNF-alpha, IL-1b, and IL-6, have diverse effects in the regulation of immune reactions and inflammation, secondary to sepsis, hence they were the ones determined in our study." (PMID 36551850, 2022). "We found that TNF-α, IL-6, and IL-1β were significantly increased in the sepsis group, offset by 3PO and Gsdmd gene deletion." (PMID 36589684, 2022). "TNF-α, IL-6, and IL-1β are involved in LPS-induced tissue damage and are regarded as major regulators of severe inflammatory diseases such as sepsis." (PMID 35038964, 2022). "Increases in the levels of TNF-α, IL-6 and IL-1β in the plasma indicated increased inflammation in the rats with sepsis." (PMID 35576220, 2022). "The EVs containing histones released by mouse-derived BMDM interact with TLR4, displaying pro-inflammatory effect, which can promote the production of TNF, IL-6 and IL-1β, thereby increasing the lethality of sepsis." (PMID 35463634, 2022). "It is assumed that neutrophil pyroptosis in sepsis controls the level of IL-1β and IL-18 and therefore the excessive inflammation." (PMID 36068299, 2022). "We found an obviously higher transcriptional levels of IL-1β and IL-18 in macrophages in Card9−/−-sepsis mice." (PMID 35618701, 2022). "Using an in vivo LPS-induced sepsis model, we measured decreased serum levels of IL-1β, IL-1α, and IL-6 as well as increased survival of mice treated with ML133 or in Lyz2-cre-Kcnj2f/f mice compared to controls." (PMID 35729093, 2022).
Sepsis (continued). "The results indicated that the compounds played anti-sepsis effect through inhibiting the release of NO, IL-1β, IL-6, and TNF-α mediated by LPS and regulating the LPS-TLR4/MD-2-NF-κB pathway by hydrophobic binding to the key protein MD-2." (PMID 36160407, 2022). "In the CLP mouse model, inhibition of the NLRP3/IL-1β pathway can alleviate sepsis-induced myocardial atrophy and cardiomyopathy and has a certain effect on the prevention of sepsis-induced cardiomyopathy." (PMID 36405697, 2022). "And the level of pro-inflammatory cytokines including (TNF-α and IL-1β) were further elevated in LysM+QKIfl/fl mice after TGX-221 treatment in MRSA induced sepsis." (PMID 36088389, 2022). "Reducing IL-1β levels through inhibition of NLRP3 in microglia was shown to improve cognitive function in sepsis." (PMID 35642838, 2022). "There was a clustering of CXCL8, TNFα, CCL4, CCL3, IL-1β and IL-6in the sepsis group indicating a chronic inflammatory response which seems to be mediated mostly by monocytes, whereas the febrile controls had no specific pattern." (PMID 35811678, 2022). "IL-1β and IL-6 are well-known pro-inflammatory cytokines and the role of IL-1β and IL-6 in sepsis has been well documented previously." (PMID 36422559, 2022). "IL-31 was able to reduce the mortality rate of lipopolysaccharide (LPS)-induced sepsis, by a reduction in the inflammatory cytokines and inhibition of IL-1β production in LPS-induced sepsis." (PMID 35742951, 2022). "IL-10 showed positive correlations with the other six cytokines studied in patients with sepsis, and with IL-1β, TNF-α, IL-6, and IL-8 in patients with septic shock." (PMID 36536294, 2022). "In OPN-/- mice, increase of these cytokines was in general moderate, with a significant decrease of IL-1β and IL-6, in line with the mild sepsis developed by these mice." (PMID 36119089, 2022). "On the other hand, children with sepsis had significantly higher levels of IL-1β, IL-12 and IL-17A compared to febrile controls, whereas only levels of IL-7 were found to be significantly lower in sepsis compared to febrile controls." (PMID 35811678, 2022). "Following sepsis, we tested candidate MK growth factors and observed decreased splenic expression of Tpo, Csf2, and Ccl5, while Il1b was unchanged and Il3 and Il6 were significantly increased." (PMID 35192546, 2022). "Compared with those in the sepsis group, the levels of IL-6, IL-1β and TNF-α were increased (P < 0.05), the MDA content was increased, while the SOD and CAT activities were decreased in the sepsis + BAY 87–2243 group (P < 0.05)." (PMID 35576220, 2022). "Second, LPS activates inflammatory cells to secrete TNF-a, IL-1β, IL-6 and other cytokines, which mediate the development of sepsis." (PMID 35664882, 2022). "Giving that changes in inflammatory factors, including TNF‐α, IL‐1β, IL‐6, IL‐10, and iNOS, are a major characteristic of the sepsis model, we measured the inflammatory cytokines after LPS treatment." (PMID 35474613, 2022). "In a lipopolysaccharide-induced macrophage model, serine supplementation promoted IL-1β secretion, whereas the inhibition of serine metabolism reduced IL-1β production in a sepsis model, while improving survival in septic mice." (PMID 36188538, 2022). "Our research showed significantly higher lung tissue levels of pro-inflammatory cytokines (IL1B, IL-6, and IL-17) in sepsis and vehicles groups compared with the sham group, corresponding to other findings." (PMID 35928365, 2022). "The levels of IL-6, TNF-α, and IL-1β in the control group were the lowest, and those in the sepsis group were the highest." (PMID 35186224, 2022). "Rs12196996 GG and rs2232365 AA were also correlated with increased level of miR-23a, IL-10 and decreased level of TNF, IL-2, IFN, IL-6 and IL-1β in the peripheral blood cell samples of patients with ICU-acquired sepsis." (PMID 35156517, 2022).
Sepsis (continued). "Prdx4 was encapsulated into EVs released by activated macrophages, inhibited caspase-1 cleavage and IL-1β maturation, and attenuated cytokine release and inflammasome activation in sepsis." (PMID 36579343, 2022). "Among these factors, TNF-α plays a key role in the pathogenesis of sepsis, and IL-1β and IL-6 participate in the initiation of the sepsis cascade and reflect the degree of inflammation." (PMID 35576220, 2022). "Substantial IL-1β, IL-6, TNF-α, and cell fragments cause renal tubular epithelial cell damage in sepsis-induced AKI." (PMID 35165294, 2022). "It reduces the level of inflammatory factors such as TNF-α and IL-1β produced by macrophages, and increases the level of macrophages derived anti-inflammatory factor IL-10, functioning protective role in sepsis." (PMID 35463634, 2022). "The expression of key inflammasome proteins NLRP3 and caspase-1 and pyroptosis-related proteins GSDMD, IL-1β, and IL-18 was decreased, suggesting that inhibition of pyroptosis also alleviated lung injury in mice with sepsis." (PMID 35188436, 2022). "The administration of Rg4 reduced cytokine levels, including TNF-α, IL-1β, and NO in the kidneys, the most sensitive organ to sepsis resulting from high-grade CLP." (PMID 36142743, 2022). "In human cells, neutralization via antibodies against IL-31 and its receptor enhanced NLRP3 expression and IL-1β activation, suggesting that the inflammasome plays a role in sepsis development." (PMID 35742951, 2022). "In patients with severe sepsis and acute lung injury, the device was reported to have reduced the levels of IL-6, IL-8, IL-1β and TNF-α21–24,46." (PMID 35882835, 2022). "IL-1b and IL-10 levels were significantly higher in patients who worsened than in those who improved only in the group of patients with sepsis with sufficient predictive value." (PMID 33917002, 2021). "NLRC4 (NLR family CARD domain containing 4) was found to be up-regulated by MAPK pathway in pediatric sepsis, which also inhibited IL‐1β and IL‐18 production to contribute to the anti-inflammatory response." (PMID 33949285, 2021). "In these studies, RIC reduced the levels the proinflammatory cytokines TNF-α, IL-1β, and IL-6, as well as suppressing the sepsis-induced increase in plasma cardiac troponin I." (PMID 34169381, 2021). "During sepsis, the release of pro-inflammatory molecule IL-1β leads to systemic inflammation, which subsequently affects the gut integrity." (PMID 35111693, 2021). "Studies have found that TNF-α and IL-1β are the main mediators of cardiac insufficiency in sepsis and are considered to be direct myocardial depressants." (PMID 34950238, 2021). "Systemic administration of IL-1β-primed MSCs increased macrophage M2 polarisation and increased the survival rate of murine sepsis only in the presence of miR-146a." (PMID 34685532, 2021). "The results of this study showed that gut-origin sepsis was associated with increased expression of the proinflammatory cytokines (TNF-α, IL-1β, IL-6, and HMGB1) and decreased expression of anti-inflammatory cytokine IL-10." (PMID 34790828, 2021). "NLRP3 knockout mice are incapable of activating IL-1β and therefore show reduced IL-1β serum levels at baseline as well as in sepsis." (PMID 34572540, 2021). "We also observed that administering IL-38 to mice with CLP-induced sepsis lowered the circulating concentrations of the proinflammatory cytokines IL-1β, IL-6, and TNF-α, while elevating systemic levels of the anti-inflammatory cytokine IL-10." (PMID 34955683, 2021). "One study reported that the caspase-1 inhibitor VX-765 reduced caspase-1 expression in the brain tissue of the sepsis mouse model and reduce the production of mature IL-1β, which inhibited pyroptosis and eventually attenuated the inflammatory response." (PMID 34305952, 2021). "The expression of IL-1β, IL-6, and IL-18 in lung tissues of sepsis-induced ALI mouse model was obviously decreased by the infection of lv-LBH (P < 0.001)." (PMID 33553423, 2021).
Sepsis (continued). "The levels of other inflammatory mediators most relevant in sepsis, including TNFa, Il-6, and Il-1b, while increased in our model of CLP, remained unchanged upon SCH772984 treatment." (PMID 34638546, 2021). "Accordingly, we observed a decrease in muscle maximal force which mirrored the increase in IL-1β mRNA gene expression in the spontaneously breathing sepsis group." (PMID 33825987, 2021). "IL-1β is an upstream pro-inflammatory cytokine, and some studies reported that blocking IL-1β also reduces immunosuppression, which results in late sepsis." (PMID 34749650, 2021). "Nevertheless, IL-1β and IL-6 were elevated in the hippocampus at P2 and P30 and in the neocortex at P8 and P30 in mice from the sepsis group." (PMID 33632243, 2021). "IL-1β is considered to be a key molecule in the mechanism underlying LTP impairment and cognitive decline in sepsis." (PMID 33643027, 2021). "NLRP3‐mediated IL‐1β activation in sepsis plays a role in in the pathogenesis of septic cardiomyopathy, leading to cardiac atrophy and decreased systolic and diastolic cardiac function." (PMID 34472725, 2021). "By contrast, different cytokines participate in sepsis progression, with increased levels of IL-1β, IL-6, IL-8, IL-12, IFN-γ, granulocyte colony-stimulating factor, and TNF-α observed in non-survivors as compared to survivors." (PMID 34884813, 2021). "TNF-α, IL-6, IL-12 and IL-1β play an important role in sepsis, and levels of TNF-α are negatively correlated with survival in septic patients." (PMID 33995024, 2021). "IL-1β-conditioned MSCs had EVs capable of attenuating murine sepsis by evoking an anti-inflammatory M2 response." (PMID 34206190, 2021). "This study provides strong evidence that IL-1β derived from activated microglia is responsible for the synaptic deficits observed in sepsis." (PMID 34062710, 2021). "Pellino1−/− mice suppressed the protein expression of Pellino1, TRAF6 and NF-κB and inhibited the levels of TNF-α, IL-6, IL-1β and IL-18 in mice of sepsis." (PMID 33632252, 2021). "Macrophage-mediated inflammation releases cytokines such as TNF-α, IL-1β, IL-6, and IL-8, which play an important role in the pathogenesis of sepsis." (PMID 34220338, 2021). "Since intraperitoneal injection of LPS is also known to induce noncanonical inflammasome via caspase-11 in the immune cells of mice, the exact mechanism whereby APPL1 controls sepsis and IL-1β production in animal model requires further investigation." (PMID 34789781, 2021). "Among them, IL-37, IL-33, IL-18, IL-1β, and IL-1α have been demonstrated to exert pleiotropic effects on various immune cells during sepsis." (PMID 34955683, 2021). "In sepsis patients, regarding inflammatory cytokines, JKAP level negatively associated with TNF-α (P = 0.008), IL-1β (P = 0.009), and IL-17 (P = 0.003) expressions." (PMID 33083958, 2021). "More importantly, suppression of NF-κB contributed to a reduction of release of LPS-induced pro-inflammatory cytokines such as TNF-α, IL-1β, and IL-6 in sepsis." (PMID 33413595, 2021). "A study shows that Scr and BUN levels, apoptotic cell scores, TNF-α and IL-1β levels, and oxidative stress are raised as well as survival rates and renal histology scores are declined in the sepsis-induced AKI30." (PMID 33785732, 2021). "In a mouse model of Pseudomonas aeruginosa-induced sepsis, Atg7 gene knockout mice showed enhanced activity of inflammasomes in macrophages, accompanied by elevated blood levels of IL-1β and IL-18 and increased pyroptosis in macrophages." (PMID 34257519, 2021). "This explains a significant increase in Tnf-α, Ifn-α, IL-1β, and IL-6 mRNAs in the LPS stimulated spleen, liver, and kidney and demonstrates the effective suppression of these key sepsis markers by MIC-1." (PMID 33793581, 2021). "NEAT1 showed a good predictive value for increased sepsis risk.NEAT1 expression was positively associated with disease severity, CRP, PCT, TNF-α, and IL-1β, 28-day deaths." (PMID 34956235, 2021).